EPO (erythropoietin)
Diseases named in the same sentence as EPO in open-access papers (continued):
Sharing a sentence is not in itself a finding about the gene and the disease.
Thrombocytosis (23 papers, 2007 to 2025). Increased numbers of platelets in the peripheral blood. "When iron supply is inadequate, intense erythropoietin stimulation may cause thrombocytosis, but when iron supply is available, erythropoiesis predominates and megakaryopoiesis may be transiently decreased." (PMID 18067664, 2007). "Anemic patients often exhibit elevated erythropoietin (EPO) levels, leading to secondary thrombocytosis." (PMID 41267874, 2025). "Studies on patients with thrombocytosis have revealed a correlation between CALR mutations and EPO levels." (PMID 40568201, 2025). "A low EPO is also used to discriminate PV from secondary thrombocytosis because it is usually seen in PV." (PMID 39421127, 2024). "In the context of IDA, there is an increase in erythropoietin secretion, which not only augments red blood cell count but also stimulates platelet production, thereby inducing thrombocytosis and thrombus formation." (PMID 39228510, 2024). "Her workup revealed an elevated hematocrit, thrombocytosis, high ferritin, and normal erythropoietin." (PMID 36458103, 2022). "Anecdotally, thrombocytosis may follow erythropoietin administration and further impact kidney perfusion." (PMID 38057431, 2024). "JAK2V617F activates erythropoietin (EPO), thrombopoietin (TPO), and granulocyte-colony stimulating factor (G-CSF) receptors in the absence of ligands, whereas exon-12 mutations activate the EPO receptor, resulting in erythroid-dominant myeloproliferation and reduced leukocytosis and thrombocytosis." (PMID 40699626, 2025). "When iron supply is lacking intense erythropoietin stimulation may cause thrombocytosis, but when the iron is amply present, erythropoiesis predominates and megakaryopoiesis may be transiently decreased." (PMID 34557594, 2021). "Low-dose erythropoietin (EPO) injection induced erythrocytosis without concomitant leukocytosis or thrombocytosis and further exacerbated plaque necrosis." (PMID 35587375, 2022). "The thrombocytosis was not due to renal overproduction of erythropoietin as the erythropoietin level was normal in our patient." (PMID 22834973, 2012). "The only hematopoietic cytokine found to be significantly elevated in this cohort was erythropoietin (EPO), which was elevated in patients with and without thrombocytosis." (PMID 22084665, 2011). "EPO alone, while expected to improve RBC transfusion requirements in some patients, would not be expected to improve thrombocytosis, as was seen in this patient." (PMID 25918650, 2015).
chronic heart failure (22 papers, 2011 to 2024). "It has been shown, that raised endogenous plasma erythropoietin concentrations in patients with congestive heart failure are associated with increased cardiovascular mortality." (PMID 28109258, 2017). "Previous studies demonstrated an independent association between higher circulating endogenous erythropoietin (EPO) levels and risk of all-cause and cardiovascular death among RTRs, similar to other patient populations such as chronic heart failure patients and the elderly." (PMID 32512806, 2020). "Prior studies conducted in various populations, including in elderly individuals, kidney transplant recipients, and in patients with chronic heart failure, found that higher EPO levels are associated with an increased risk of death, even independent of hemoglobin levels." (PMID 31170159, 2019). "In the setting of chronic heart failure and cardiac surgery, treatment with iron supplementation and/or erythropoietin has been suggested as an effective measure to improve the outcome." (PMID 38682100, 2024). "In mice, overexpression of eNOS attenuated congestive heart failure and improved survival and EPO protection against ischemia-reperfusion injury requires eNOS activity." (PMID 38628440, 2024). "In humans, treatment with EPO improved ejection fraction and clinical outcomes in patients with congestive heart failure." (PMID 34339435, 2021). "The first clinical trial of EPO in patients with chronic heart failure gave promising findings of increased exercise capacity and cardiac function." (PMID 22863174, 2012). "A recent clinical study has shown that EPO is still relatively safe to treat chronic heart failure." (PMID 39624122, 2024). "High-preoperative RBC-DW could result from the decrease in erythropoietin (EPO) production and chronic heart failure, increasing the in-hospital mortality with AKI after cardiac surgery." (PMID 34635052, 2021). "Furthermore, EPO treatment in a rat model for chronic heart failure suggested that long term EPO treatment stimulated homing of endothelial progenitor cells to induce neovascularization." (PMID 32038269, 2019). "EPO serum could decrease in these situations such as chronic anemia, liver dysfunction, elderly, dementia but increase in hypoglycemia, head trauma or surgery history, hematologic disease, malignancy, atrial fibrillation, congestive heart failure." (PMID 38302546, 2024). "Similarly, higher circulating endogenous erythropoietin (EPO) levels have been associated with an increased all-cause and cardiovascular mortality risk in various disease populations, including chronic heart failure patients, kidney transplant recipients, and elderly individuals." (PMID 31170159, 2019). "Another study reported that the ESA erythropoietin increased exercise tolerance, lowered the NYHA class, improved renal function, and reduced the BNP levels in patients with chronic heart failure." (PMID 36979925, 2023). "Congestive heart failure (CHF) and chronic kidney failure (CKF) lead to progressive renal dysfunction and a decrease in EPO levels, with reduced erythrocyte production by bone marrow." (PMID 22748015, 2012).
glaucoma (21 papers, 2012 to 2025). Increased pressure in the eyeball due to obstruction of the outflow of aqueous humor. "In contrast, activation of the NRF2/ARE pathway by PLGA.EPO-R76E in glaucoma caused increased expression of Gpx 3, Prdx2, and Prdx6." (PMID 36978804, 2023). "The DBA/2J mice, which spontaneously develop glaucomatous loss of RGC and are used to mimic human hereditary glaucoma, were intraperitoneally injected with EPO." (PMID 35806148, 2022). "Due to the complex pathogenesis of glaucoma, EPO was developed to prevent the IOP-independent RGCs loss." (PMID 35806148, 2022). "Technological advancements, such as next-generation sequencing, would expectedly broaden our understanding of the underlying mechanisms of both the disease course of glaucoma and EPO signaling pathways involved in its therapeutic effects." (PMID 36555679, 2022). "Many studies have demonstrated that EPO production is associated with glaucoma." (PMID 36769310, 2023). "However, there were very few reports on the preventative effects of EPO on RGC death caused by glaucoma or chronic neurodegenerative diseases." (PMID 32302311, 2020). "Erythropoietin (EPO), known for its anti-apoptotic, antioxidant, and anti-inflammatory effects, has shown promise for neuroprotection in glaucoma." (PMID 39796087, 2024). "We foresee future studies that address EPO with better-controlled regulation to magnify its therapeutic effects in glaucoma." (PMID 36769310, 2023). "EPO-level increase in glaucoma is considered as a compensatory neuroprotective action secondary to glaucomatous damage." (PMID 36769310, 2023). "Previous studies have shown that EPO reduces cell death, axon degeneration and oxidative stress in multiple models of glaucoma." (PMID 36978804, 2023). "The intravitreal injection of PLGA.EPO-E76E in glaucoma mice displayed neuroprotective activity and prevented increases of retinal •O2—levels and caused activation of the NRF2/ARE antioxidant pathway." (PMID 37376219, 2023). "Using an inhibitor of MAPK, BIRB 796, we determined that inhibition of MAPK prevents EPO’s antioxidant and neuroprotective effects in the microbead occlusion model of glaucoma." (PMID 36978804, 2023). "One study reported that the EPO concentration in the aqueous humor is increased in eyes with primary open-angle glaucoma, pseudoexfoliation glaucoma, and neovascular glaucoma." (PMID 36769310, 2023). "In this study, we aimed to determine if EPO-R76E loaded PLGA microparticles (PLGA.EPO-R76E) would protect against downstream neurodegeneration in the well-characterized microbead occlusion model (MOM) of glaucoma." (PMID 36978804, 2023). "This article explores the relationship between EPO and glaucoma and summarizes preclinical experiments that have used EPO to treat glaucoma, with an aim to provide a different perspective from the current view that glaucoma is incurable." (PMID 36769310, 2023). "The antiapoptotic, anti-inflammatory, and antioxidative effects of EPO make it a promising therapeutic for treatment of glaucoma." (PMID 36769310, 2023). "Since EPOβ is a recombinant human EPO commonly used in medical practice, it was selected for this study with the perspective of contributing for glaucoma treatment as a neuroprotective agent." (PMID 36707615, 2023). "To determine the signaling pathway involved in EPO-mediated phosphorylation of NRF2 in glaucoma, we assessed the ratio of phosphorylated to total PI3K, Akt, JNK, STAT1, STAT3, GSK3β, and MAPK." (PMID 36978804, 2023). "Our study shows that EPO, in the context of glaucoma, induces NRF2 phosphorylation using a different pathway than the retina’s endogenous antioxidant response to elevated IOP." (PMID 36978804, 2023). "Various in vitro and in vivo animal models have been used to explore the potential therapeutic effects of EPO in glaucoma or RGC survival." (PMID 36555679, 2022).
glaucoma (continued). "Clinically applying EPO treatment in patients with glaucoma is hindered by safety concerns of its pro-angiogenic activity, as EPO was found to participate in some pathological conditions." (PMID 36555679, 2022). "In humans, there are only a few observational studies investigating the correlation between EPO and glaucoma, especially neovascular glaucoma." (PMID 35806148, 2022). "Larger randomized clinical trials are still needed in the future to verify the neuroprotective effects and evaluate possible adverse events of EPO in humans with glaucoma." (PMID 36555679, 2022). "Without affecting the IOP level, EPO promoted RGC survival in DBA/2J glaucomatous mice, indicating EPO as a potential therapeutic neuroprotectant in glaucoma." (PMID 36555679, 2022). "EPOβ, a recombinant human EPO, was chosen as an active principle due to its potential neuroprotective and neuroregenerative qualities, with the perspective of helping in glaucoma treatment." (PMID 35200680, 2022). "Subconjunctival injection of EPO in a rat model of glaucoma demonstrated increase in electroretinography wave amplitudes and retinal thickness." (PMID 35806148, 2022). "Apart from our previous research results, EPO was also found to be neuroprotective via systemic, intravitreal, subconjunctival and retrobulbar administration in rat model of glaucoma." (PMID 35806148, 2022). "Previous studies have also found a significantly higher aqueous levels of EPO in primary open-angle glaucoma, acute and chronic primary angle-closure glaucoma, neovascular glaucoma, and pseudoexfoliative glaucoma." (PMID 36555679, 2022). "Owing to its neuroprotective potential, researchers have explored the therapeutic effects of EPO in optic neuropathies, particularly glaucoma." (PMID 36555679, 2022). "A further study with a similar design showed that subconjunctival EPO administration exerted beneficial effects on retina both structurally and functionally in induced glaucoma in Wistar albino rats." (PMID 36555679, 2022). "In conclusion, EPO and its derivatives continue to be a promising and novel treatment modality for glaucoma other than IOP-lowering agents." (PMID 36555679, 2022). "Several studies have reported that the EPO level in the aqueous humor increased in patients with glaucoma." (PMID 35806148, 2022). "In this review, we introduce and discuss the neuroprotective function of the EPO/EPOR system and the latest evidence of the treatment of glaucoma with EPO." (PMID 36555679, 2022). "As a result, they concluded that a single IVI of 200 ng EPO exerted protective effects on RGC viability in an in vivo rat model of glaucoma." (PMID 36555679, 2022). "EPO and PDGFs elevations have been detected in primary open angle glaucoma and neovascular glaucoma." (PMID 34384366, 2021). "The DBA/2J mouse progressively develops a mouse model of glaucoma, and these mice were injected at 5 months of age with EPO.R76E, intramuscularly." (PMID 33920974, 2021). "However, little is known about how EPO signal transduction occurs in vivo and the practical usefulness of EPO in the prevention of chronic purely apoptotic neuronal cell death, which contributes to vision loss in glaucoma and the progression of neurodegenerative diseases." (PMID 32302311, 2020). "Future studies will focus on the neuroprotective effects of EPO on human ganglion cells to explore its potential application for glaucoma patients." (PMID 32302311, 2020). "The goal of this study was to exploit the efficacy of EPO in blocking glaucoma pathogenesis in order to investigate the mechanisms responsible for this axonopathy in the DBA/2J model." (PMID 26876380, 2016). "• Erythropoietin made a trial on a mouse model of glaucoma; in this trial, erythropoietin promoted RGC survival." (PMID 25914734, 2015). "In patients with glaucoma, erythropoietin (EPO) is increased in the aqueous humor, exerting a protective effect on the photoreceptors, RPE, and ganglion cells." (PMID 26558262, 2015).
glaucoma (continued). "In simple regression analysis, IOP, mean deviation, and the type of glaucoma were the factors that had a statistically significantly positive correlation with the aqueous level of EPO (p=0.011 and <0.001, respectively)." (PMID 22876126, 2012). "The mean±SEM aqueous level of EPO was statistically significantly higher in eyes with glaucoma (56.7±9.3 mIU/ml) compared to the control group (0.8±0.51 mIU/ml; p<0.001)." (PMID 22876126, 2012). "Aqueous EPO concentrations remained considerably elevated even in eyes with controlled IOP in all three types of glaucoma." (PMID 22876126, 2012). "Several studies have shown that EPO concentration is increased significantly in the aqueous humor of eyes with primary open-angle glaucoma compared to eyes with only cataracts (controls)." (PMID 22876126, 2012). "We also assessed the association between the aqueous level of EPO and other factors, including age, gender, intraocular pressure (IOP), severity of visual field defect, and type of glaucoma." (PMID 22876126, 2012). "Determinants of erythropoietin level in aqueous humor of glaucoma patients in simple and multiple regression analyses." (PMID 22876126, 2012). "The difference was not statistically meaningful between PXFG and POAG (p=0.925), but both had significantly higher levels of EPO than non-glaucoma patients (p=0.041 and p=0.021, respectively)." (PMID 22876126, 2012). "Simple regression analysis showed that the level of IOP, mean deviation, and type of glaucoma had a significant correlation with the aqueous concentration of EPO (p=0.011 and p<0.001, respectively)." (PMID 22876126, 2012). "Interestingly, elevated EPO levels have also been detected in the aqueous humor of glaucoma patients, possibly reflecting an endogenous attempt to counteract retinal stress." (PMID 40943905, 2025). "Adeno-associated virus (AAV) vectors are currently the predominant choice for glaucoma gene therapy delivery, encoding genes such as BDNF, EPO, and NRF2, enabling uncontrolled expression of target genes in AAV-transduced cells in both in vivo and in vitro models." (PMID 39744428, 2025). "Therefore, we summarized the relationship between EPO and glaucoma and comprehensively reviewed research related to EPO in glaucoma treatment." (PMID 36769310, 2023). "Below, we summarize the latest studies about EPO for glaucoma." (PMID 36769310, 2023). "Based on the experimental results above and the molecular pathway of EPO, administration of EPO might have therapeutic potential in treating glaucoma." (PMID 36769310, 2023). "However, recombinant EPO is limited in clinical treatment of glaucoma patients due to its short half-life." (PMID 35806148, 2022). "Future studies could focus the application of EPO in patients with primary open-angle glaucoma to see if EPO exhibits the same neuroprotective effects in animal experiments." (PMID 35806148, 2022). "Therefore, research focusing on the therapeutic effect of EPO in glaucoma has been studied both locally and systemically." (PMID 36555679, 2022). "Consequently, there is a growing interest in the study of the potential therapeutic effects of EPO in glaucoma patients." (PMID 36555679, 2022). "A single intravitreal injection of EPO could provide protective effects on RGC viability in rat model of glaucoma." (PMID 35806148, 2022). "Another group utilized a recombinant adeno-associated virus (rAAV) encoding EPO.R76E, a form of EPO with attenuated erythropoietic activity that has been shown to preserve RGC axons, cell bodies, and vision in the DBA/2J model of glaucoma." (PMID 33920974, 2021). "EPO expression is also increased in glaucoma patients and in a rat model of ocular hypertension suggesting that it may represent an endogenous protective mechanism." (PMID 26876380, 2016). "Others have also shown that injections of EPO protein are effective in glaucoma models." (PMID 26876380, 2016).